PLD2 (phospholipase D2)
Diseases named in the same sentence as PLD2 in open-access papers (continued):
Sharing a sentence is not in itself a finding about the gene and the disease.
tumor (continued). "Here, we demonstrate that PLD2 in cytotoxic CD8+ T cells plays a crucial role in anti-tumor immunity by regulating their cell proliferation." (PMID 29674728, 2018). "In 81% of all analysed tumours PLD2 expression as well as phospho-Akt and mTOR activity were elevated while the expression of LKB1 was decreased." (PMID 28649994, 2017). "We provide evidence about the beneficial effect of PLD inhibitors [FIPI (dual PLD1/PLD2) or VU0155072-2 (PLD2 inhibitor)] on avoiding infiltration of tumor-helping macrophages and neutrophils." (PMID 27851813, 2016). "MiR-203 has been reported as a novel tumor and metastasis suppressor by directly targeting mRNA of PLD2, Bmi-1 and PKCα." (PMID 25373785, 2014). "An obvious correlation was observed between PLD2 expression and the tumor size as well as patient survival." (PMID 24103483, 2014). "PLD2 bypasses cell cycle arrest programs that are often activated by apoptotic pathways, leading to tumor progression." (PMID 27713341, 2010). "PLD2 regulates various cellular processes such as proliferation, adhesion, survival, apoptosis and tumor transformation." (PMID 27713341, 2010). "Importantly, the increase in CSC-like features induced by hypoxia relies on PLD2 expression, indicating that the hypoxia-PLD2 axis is a major contributor to tumor stemness." (PMID 38403587, 2024). "Finally, we performed in vivo analyses to validate our findings by establishing xenograft models from SKOV3 and OVCAR8 cells overexpressing PLD2 or parental cells and analyzing tumor growth upon treatment with cisplatin." (PMID 38403587, 2024). "But this study also mentions that the effect of PLD2 on tumor may be twofold: on the one hand, it can lead to tumor progress, but on the other hand, it can result in an arrest in tumor cell growth." (PMID 38706911, 2024). "We observed that the overexpression of PLD2 in OC cells led to a significant increase in the number of clones generated by the three cell lines, while a significant decrease was detected in the OVCAR8 cells upon PLD2 depletion, suggesting that PLD2 promotes tumor growth." (PMID 38403587, 2024). "However, the possibility that PLD2 in other immune cells are also involved in suppression of tumor growth cannot be excluded." (PMID 36131027, 2022). "Thus, it can be concluded that PLD2 in CD8+ T cells plays an important role in the anti-tumor immunity." (PMID 29674728, 2018). "Since PLD2 has been reported to promote the EGF receptor (EGFR) endocytosis through the activation of the Dynamin GTPase39, PLD2 might inhibit the EGF/EGFR circuit among tumor cells and stromal cells by limiting cell surface EGFR of stromal cells." (PMID 29674728, 2018). "However, extent of tumor growth in rWTdKO was less than that in rKOdKO, indicating that PLD2 in other cell types distinct from bone marrow cells is also involved in the tumor growth suppression." (PMID 29674728, 2018). "To confirm this idea, we examined whether ablation of Pld2 in CD8+ T cells is responsible for enhanced tumor growth." (PMID 29674728, 2018). "An increase in PLD2 levels was reported, in which PLD2 expression varied from tumor to tumor." (PMID 24103483, 2014). "Finally, a role of PLD1 and PLD2 inducing exosome secretion in OC cells has also been recently proposed, suggesting that PLD2 may also influence the tumor microenvironment in OC." (PMID 38403587, 2024). "Finally, we extended the gene expression analyses to EMT genes using TaqMan Arrays to assess whether PLD2 expression may have a role in tumor invasion and metastasis." (PMID 38403587, 2024). "Thus, it is likely that PLD1 and PLD2 have differential roles in tumor immunity." (PMID 36131027, 2022). "(ii) PA might contribute to the trafficking and secretion of factors that promote tumor progression; a potential role for PA generated by PLD2 in secretion of Type 1 Matrix metalloproteases, enzymes that are implicated in metastasis, has recently been presented." (PMID 31231646, 2019).
tumor (continued). "HMGB2 in POSTN+ fibroblasts is predicted to bind to PLD2, LRP5, MYLK, and CD44 on tumor cells, regulating downstream genes, including BIRC5, CCNA2, CCNB1, CCNB2, CDC20, and MKI67, which are related to the cell cycle." (PMID 38519500, 2024). "Sondra and his colleagues have previously shown that PLD2 expression was increased in CRC and was correlated with lower survival rate and faster tumor growth." (PMID 38706911, 2024). "Among these DETs, multiple genes, including STAT3, PDGFA, PLD2, and PIK3R2, have been reported to be involved in tumor growth." (PMID 35291563, 2022). "Collectively, these results indicate that PLD2 in CD8+ T cells plays a key role in their proliferation through activation of the Ras/Erk signaling pathway, thereby regulating anti-tumor immunity." (PMID 29674728, 2018). "In the present study, we focused on the function of PLD2 in CD4+ and CD8+ T cells to elucidate the pathological function of PLD2 in tumor growth." (PMID 29674728, 2018). "When PLD2 was silenced in MDA-MB-231 cells, which were transplanted into mice, primary tumor size was reduced when compared with normal tumors." (PMID 24103483, 2014). "For instance, enzymes like phospholipase D2 (PLD2) and certain sphingolipids, which are abundant in sEVs lipid content, are critical for releasing multivesicular bodies and stimulating sEVs secretion from tumor cells." (PMID 40008006, 2025). "Then, we separated our patient samples into those who were sensitive or resistant to platinum-based chemotherapy (without or with tumor relapse within the next 6 months after chemotherapy, respectively) and analysed PLD2 expression levels." (PMID 38403587, 2024). "Unlike the previous reports showing tumor-progressive functions of PLDs14,16, tumor growth was significantly enhanced in Pld2−/− mice." (PMID 29674728, 2018). "As we have demonstrated that overexpression of PLD2 in cell culture results in increased activity of LKB1 (reflected by enhanced AMPK activation), we next assessed the pathophysiological relevance of our findings regarding tumour formation in vivo." (PMID 28649994, 2017). "Protein kinase C alpha is specifically linked to activation of PLD1 and PLD2; results show that a PKCα link to PLD is active in cell lines derived from both normal and tumourigenic epithelia, including P4E6 cells derived from an early tumour." (PMID 21266973, 2011). "Moreover, although treatment with cisplatin alone did not reduce the higher tumor growth induced by PLD2 overexpression, its combination with PLDi led to a further reduction in tumor growth." (PMID 38403587, 2024). "However, tumors overexpressing PLD2 showed higher tumor growth that was not reduced upon cisplatin treatment, indicating both a higher aggressiveness of PLD2- overexpressing tumors and the resistance of these tumors to cisplatin." (PMID 38403587, 2024). "However, we cannot still rule out the possibility that PLD2 in other immune cells is also involved in suppression of tumor growth." (PMID 29674728, 2018). "Similarly, number of CD8+ T cells but not CD4+ T cells in the LLC tumor formed in Pld2−/− mice was decreased." (PMID 29674728, 2018). "On the other hand, we did not observe any changes in tumor angiogenesis in Pld2−/− mice, even though PLD2 could be deleted from vascular endothelial cells in these mice." (PMID 29674728, 2018). "However, neither the involvement of PLD2 in the tumor microenvironment nor the link between PLD2-mediated immune responses and tumor immunity has been elucidated." (PMID 29674728, 2018). "Although we showed that PLD2 is critical for proliferation and survival of activated CD8+ T cells, thereby contributing to suppression of tumor growth, PLD2 in other types of cells distinct from immune cells might be also involved in the suppression of tumor growth." (PMID 29674728, 2018). "Thus, enhancement of tumor growth in Pld2−/− mice is not related to tumor angiogenesis." (PMID 29674728, 2018).
infection (3 papers, 2019 to 2024). The state of being infected such as from the introduction of a foreign agent such as serum, vaccine, antigenic substance or organism. "In order to explore the biological functions of PLD2 in human CRC cells, a further experiment was performed by constructing PLD2 knockdown stable cell line through lentiviral infection." (PMID 38706911, 2024). "Two other novel miRNAs, pol-miR-n008-3p and pol-miR-n370-3p, targeted PLD2 and MET, respectively, which have been reported to contribute to the infection and internalization of Yersinia enterocolitica and Listeria monocytogenes, respectively." (PMID 32549342, 2020).
cardiovascular disease (2 papers, 2019 to 2020). "Meanwhile, genetic deletion or pharmacological inhibition of PLD1, PLD2, or both of PLD1 and PLD2, did not result in a prolonged bleeding time, suggesting that PLD inhibition might be a safe strategy to prevent cardiovascular diseases." (PMID 32971863, 2020).
PLD2 also shares sentences with these, for which no sentence is quoted: cardiomyopathy (2 papers); neurological disease (2); retinal degeneration (2); acute lung injury (1); Anosmia (1); bipolar disorder (1); brain injury (1); chronic asthma (1); hepatocellular carcinoma (1); hyperlipidemia (1); inflammatory bowel disease (1); Insulin resistance (1); Lewis lung carcinoma (1); lung adenocarcinoma (1); lupus (1); malignant glioma (1); metabolic disorders (1); myocardial ischemia (1); neurodegenerative disease (1); prostate (1); rheumatoid arthritis (1); skeletal diseases (1); thrombotic disease (1); viral disease (1).